RNU6-477P (RNA, U6 small nuclear 477, pseudogene)
Gene: Small nuclear RNA gene on chromosome 5 (169,552,449 to 169,552,555, forward strand). Ensembl gene ENSG00000206614.
Homologues: Orthologues: chimpanzee U6 (99% identical), macaque U6 (93% identical), mouse Gm22069 (90% identical), guinea pig U6 (87% identical), pig U6 (87% identical), dog U6 (83% identical), pig U6 (83% identical), rat LOC120098051 (79% identical). Paralogues in human: RNU6-1145P (93% identical), RNU6-38P (93% identical), RNU6-73P (93% identical), RNU6-20P (92% identical), RNU6-224P (92% identical), RNU6-1316P (91% identical), RNU6-166P (91% identical), RNU6-25P (91% identical), RNU6-41P (91% identical), RNU6-639P (91% identical), RNU6-1 (90% identical), RNU6-15P (90% identical), and 1288 more.